HRH1 (histamine receptor H1)
Diseases named in the same sentence as HRH1 in open-access papers (continued):
Sharing a sentence is not in itself a finding about the gene and the disease.
infection (5 papers, 2015 to 2024). The state of being infected such as from the introduction of a foreign agent such as serum, vaccine, antigenic substance or organism. "Albeit, the ingenuity connectome showed that lipids and cholesterol were found to be prominently linked with receptors like HRH1/VLDLR and altered function of these receptors has a significant role in infection-related neuroinflammation." (PMID 37876925, 2023). "Following fluorescently labeled H37Ra or H37Rv infection, HRH1 suppressed the fusion of phagosomes and lysosomes." (PMID 36000734, 2022). "Our above results showed that HRH1 could independently promote SARS-CoV-2infection and enhance ACE2-dependent SARS-CoV-2 entry for various viral mutants.We speculated that antihistamine drugs targeting HRH1 might prevent infection byother SARS-CoV-2 mutants." (PMID 38953634, 2024). "We also evaluated the HRH1-mediated enhancement of infection byadditional viral mutants." (PMID 38953634, 2024). "The results showed that the overexpression of HRH1 inHEK293T cells also significantly enhanced the infection of several pseudotypedSARS-CoV-2 mutants, including D614G, Delta, BA.1, BA.2, BA.2.12.1, and BA.4,demonstrating the universal utilization of HRH1 for SARS-CoV-2 infection." (PMID 38953634, 2024). "Therefore, we transiently overexpressed serially increasedamounts of HRH1-expressing plasmids in HEK293T cells, followed by infection withSARS-CoV-2 D614 PsVs at 24 h post-transfection (hpt)." (PMID 38953634, 2024). "Interestingly, uponco-overexpression of both HRH1 and hACE2 in HEK293T-hACE2-KO cells, HRH1significantly enhanced hACE2-mediated SARS-CoV-2 D614 PsV infection." (PMID 38953634, 2024). "Flow cytometric analysis indicated that in the presence of HRH1, H37Ra or H37Rv infection did not induce significant production of cytosolic ROS (cROS), whereas cROS production was enhanced by mycobacterial infection in the absence of HRH1." (PMID 36000734, 2022).
adenocarcinoma (1 paper, 2016). A common cancer characterized by the presence of malignant glandular cells. "Adenocarcinoma cells immunohistochemically expressed Hrh1, Hrh2, Hrh3 and Hrh4 with varied intensities." (PMID 26907350, 2016).
HRH1 also shares sentences with these, for which no sentence is quoted: urticaria (10 papers); atopic dermatitis (9); depression (7); allergic asthma (6); anaphylactic shock (6); Alzheimer disease (5); colorectal cancer (5); insomnia (5); neurological diseases (4); acute myocardial infarction (3); cardiovascular disease (3); chronic spontaneous urticaria (3); dyslipidemia (3); lung carcinoma (3); psoriasis (3); agranulocytosis (2); allergic conjunctivitis (2); amnesia (2); amyotrophic lateral sclerosis (2); bipolar disorder (2); brain injury (2); cardiac disease (2); Cognitive impairment (2); conjunctivitis (2); delirium (2); dermatitis (2); endometrioid adenocarcinoma (2); esophagitis (2); Hay fever (2); heart failure (2).
A further 78 diseases each share a sentence with HRH1 in 2 papers or fewer.